HCAR1 (hydroxycarboxylic acid receptor 1)
Diseases named in the same sentence as HCAR1 in open-access papers (continued):
Sharing a sentence is not in itself a finding about the gene and the disease.
epilepsy (2 papers, 2022 to 2024). A brain disorder characterized by episodes of abnormally increased neuronal discharge resulting in transient episodes of sensory or motor neurological dysfunction, or psychic dysfunction. "Taken together, our results underscore the importance of investigating HCAR1 as a potential avenue for new therapeutic approaches in epilepsy." (PMID 38655197, 2024). "Overall, we propose that lactate can be considered a neuromodulatordecreasing synaptic activity in human and rodent brains, which makes HCAR1 anattractive target for the treatment of epilepsy." (PMID 35240875, 2022). "However, synthetic HCAR1 agonist administration in an in vivo epilepsy model did not modulate seizures, likely due to endogenous lactate competition." (PMID 38655197, 2024). "The administration of a synthetic HCAR1 agonist failed to modulate seizures in an in vivo epilepsy model, possibly due to competition with elevated endogenous lactate levels during seizures, underscoring the intricate interplay between exogenous and endogenous HCAR1 modulators." (PMID 38655197, 2024).
gastric cancer (2 papers, 2024 to 2025). A primary or metastatic malignant neoplasm involving the stomach. "However, the contribution of lactate metabolism and its receptor, hydroxycarboxylic acid receptor 1 (HCAR1), in ferroptosis regulation in gastric cancer (GC) remains poorly understood." (PMID 41050072, 2025).
Hyperglycemia (2 papers, 2020 to 2021). An increased concentration of glucose in the blood. "In fact, increased body weight and hyperglycemia were associated with reduced expression of HCAR1 in BAT of male C57BL/6J mice fed HFD, consistent with reduced HCAR1 expression in adipose tissue of DIO male and ob/ob mice." (PMID 31999787, 2020). "In contrast, upregulated HCAR1 expression in BAT from female C57BL/6J mice fed HFD appears to prevent hyperglycemia and body weight gain." (PMID 31999787, 2020). "We found that there was sexual dimorphism in HCAR1 expression in BAT from mice fed HFD that may contribute to the development of hyperglycemia in male C57BL/6J DIO mice." (PMID 31999787, 2020). "Decreased expression of HCAR1 in white as well as brown adipose tissue of male mice may result in hyperglycemia in obese male animals." (PMID 31999787, 2020). "Therefore, our results suggest that HCAR1 in BAT may contribute to the development of hyperglycemia in male C57BL/6J DIO mice." (PMID 31999787, 2020). "Hyperglycemia was found to augment the expression of GLUT-1, MCT-1, MCT-4, HCAR-1, and MDR-1." (PMID 34692517, 2021).
liver cancer (2 papers, 2023 to 2024). An epithelial or non-epithelial malignant neoplasm that arises from the liver. "It has been revealed that the lactate inhibited the ferroptosis of liver cancer cells through the HCAR1/MCT1-SREBP1-SCD1 pathway, which potentially contributes to tumor metastasis and development." (PMID 38742521, 2024). "Excessive lactic acid upregulated the expression of hydroxycarboxylic acid receptor 1 (HCAR1) and monocarboxylate transporter 1 (MCT1) and inhibited ferroptosis of liver cancer cells by reducing the lipid peroxidation of liver cancer." (PMID 37213276, 2023).
melanoma (2 papers, 2020 to 2022). A malignant, usually aggressive tumor composed of atypical, neoplastic melanocytes. "HCAR1 is an additional receptor isoform and has low expression levels in both normal skin and in melanoma samples." (PMID 33028392, 2020).
adrenoleukodystrophy (1 paper, 2023). A peroxisomal disorder resulting in cerebral demyelination, axonal dysfunction in the spinal cord leading to spastic paraplegia, adrenal insufficiency and in some cases testicular insufficiency. "Upon lactate stimulation, additional neurologic disorders were also linked to the HCAR1-mediated transcriptional network, such as Huntington’s disease and adrenoleukodystrophy (ALD)." (PMID 37940970, 2023).
clear cell carcinoma (1 paper, 2022). "In cases of clear cell carcinoma (CCC), clear cytoplasmic regions are surrounded with connective trabeculae and show higher HCAR1 expression within glandular regions." (PMID 36615018, 2022).
Hypoglycemia (1 paper, 2025). A decreased concentration of glucose in the blood. "In conclusion, our findings support a role of HCAR1 in axonal development and in lactate’s protective effects in hypoglycemia." (PMID 40345852, 2025). "In conclusion, our findings strongly indicate HCAR1 involvement in axonal development and suggest that lactate, acting partly through HCAR1, exerts protective effects in experimental neonatal hypoglycemia." (PMID 40345852, 2025). "As with the axonal data, these results indicate that HCAR1 can help rescue myelination during hypoglycemia." (PMID 40345852, 2025). "Our findings reveal new roles of the lactate receptor HCAR1 in brain development and as a therapeutic target for neonatal hypoglycemia." (PMID 40345852, 2025). "Using an organotypic brain slice model of neonatal hypoglycemia, we find that lactate protects both axonal and myelin development in hypoglycemia, partially via HCAR1." (PMID 40345852, 2025). "We demonstrate that HCAR1 influences axonal size, particularly in unmyelinated axons, and mediates lactate’s protective effects during neonatal hypoglycemia." (PMID 40345852, 2025). "Additionally, our ex vivo model of neonatal hypoglycemia shows that lactate protects axonal and myelin development and that HCAR1 plays a role in this protective effect." (PMID 40345852, 2025). "Furthermore, our data propose that HCAR1 plays a role in lactate protection in hypoglycemia as lactate treated HCAR1 KO slices had poorer axonal and myelin development relative to WT." (PMID 40345852, 2025). "The HCAR1 agonist 3,5-DHBA failed to save the axonal loss in hypoglycemia, but slices from HCAR1 KO displayed more loss relative to WT (%NF200/Control: WTHG_DHBA 49 ± 28, KOHG_DHBA 22 ± 11, pHG_DHBAWT-KOp < 0.001)." (PMID 40345852, 2025). "While lactate could completely rescue myelination in hypoglycemia in slices from WT mice, the HCAR1 KO slices failed to fully restore myelination (%MBP/Control: WTHG_Lactate 89 ± 22, KOHG_Lactate 61 ± 28, pHG_LactateWT-KOp < 0.001)." (PMID 40345852, 2025).
ischemic heart disease (1 paper, 2025). "Furthermore, lactate-induced angiogenesis via HCAR1 could support vascular repair in ischemic heart disease and HCAR1 might play a role in substrate regulation during times of stress when the heart down-regulates its use of lipids and upregulates lactate-consumption." (PMID 41160759, 2025).
osteosarcoma (1 paper, 2025). A usually aggressive malignant bone-forming mesenchymal neoplasm, predominantly affecting adolescents and young adults. "In the present study, it is found that in osteosarcoma, lactate‐activated HCAR1 promotes β‐arrestin 2 translocation from cytoplasm to nucleus." (PMID 40956299, 2025).
serous ovarian cancer (1 paper, 2022). "Based on the staining in HGSOC and low-grade serous ovarian cancer (LGSOC), HCAR1 appears localised to the membrane of papillary cells with less intense (light brown) staining seen in the surrounding stroma." (PMID 36615018, 2022).
type 2 diabetes (1 paper, 2020). "As the activation of HCAR1 in BAT induces antilipolytic and antidiabetic effects, our findings have potential to lead to the discovery of novel therapeutic targets for better treatment of type 2 diabetes." (PMID 31999787, 2020).
tumor (120 papers, 2015 to 2026). "First, due to resource constraints, we were unable to perform in vivo validation experiments to assess the functional relevance of HCAR1 in tumor progression and iron mutation sensitivity." (PMID 41050072, 2025). "However, recently, elevated HCAR1 expression was also implicated in tumour growth and metastasis in cancers, such as breast and pancreatic." (PMID 36615018, 2022). "GPR81 (HCAR1) is a lactate-sensing G protein-coupled receptor (GPCR) involved in tumor progression, immune evasion, and therapeutic resistance across various cancers." (PMID 41726659, 2026). "The results revealed that either HCAR1 knockout or the addition of Endothall significantly increased the phosphorylation level of STAT1/2 in tumor tissues of mice." (PMID 40956299, 2025). "The study revealed that HCAR1 knockout reduced tumor volume, slowed growth rate, and decreased tumor weight, effects comparable to those of Endothall‐treated wild‐type cells at the study's conclusion." (PMID 40956299, 2025). "Intriguingly, however, the effects of HCAR1 and HCAR2 on tumor growth are diametrically opposed: HCAR1 is a tumor promoter, while HCAR2 is a tumor suppressor." (PMID 40233099, 2025). "In the TCGA-STAD dataset, AKR1C2 exhibited reduced expression in the tumor group; conversely, HCAR1, KRAS, and PHKG2 showed increased expression in the tumor group." (PMID 41050072, 2025). "HCAR1 is expressed on the membrane of various cells, including tumor cells, and its activation through lactate binding results in increased MCT1 expression, thereby facilitating lactate uptake by tumor cells." (PMID 40612939, 2025). "Tumor volume and mass markedly increased in mice injected with HCAR1-expressing WT-rescue cells compared with tumors silenced for HCAR1 and N-HCAR1 KD cells (δS305A rescue)." (PMID 39904567, 2025). "It has been established that elevated levels of lactate in GBM can stimulate the expression of MCT1 and HCAR1 to promote the proliferation of tumor cells." (PMID 40244246, 2025). "In vivo experiments confirmed that blocking HCAR1/β‐Arrestin2/PP2A signaling axis suppressed tumor growth and metastasis, and augmented the therapeutic efficacy of cisplatin." (PMID 40956299, 2025). "Lactate interactions with HCAR1 in cancer cells promote angiogenesis, tumor growth, and chemoresistance, and proliferation and migration of normal cells." (PMID 39529665, 2024). "In tumor cells, lactate regulates expression of HCAR1 mRNA via STAT3 (signal transducer and activator of transcription factor 3) cell signaling." (PMID 39529665, 2024). "This amassed lactic acid serves a pivotal role as a molecular activator, zeroing in on and invigorating the hydroxycarboxylic acid receptor 1 (HCAR1) ensconced on the tumor cell surface." (PMID 37860928, 2023). "Lactate, through the activation of HCAR1, can promote tumor cell proliferation, invasion, and metastasis, while inhibiting immune cell function, thereby providing favorable conditions for tumor growth and metastasis." (PMID 38203486, 2023). "Abrogating HCAR1-mediated lactate signaling sensitized tumors to anti-PD-1 and metformin treatment, leading to reduced tumor volume and increased CD8+ T cell infiltration and IFNg production." (PMID 37842241, 2023). "To further assess the signalling potential of circulating lactate in the OvCa tumour microenvironment, we explored expression of its cognate receptor, HCAR1, in normal and cancer tissues." (PMID 36615018, 2022). "These variants were exclusively identified in HCAR1 and HCAR3, which is notable considering their suggested oncogenic role and requirement for BC proliferation/survival compared to the demonstrated tumor suppressor properties of HCAR2." (PMID 34852802, 2021). "Our observations are in line with recent evidence indicating that the HCAR1 levels correlate to the rates of cancer tumour growth and metastasis." (PMID 26208712, 2015).
tumor (continued). "Accordingly, it can be speculated that interfering with lactate transport by inhibiting the expression of MCTs and HCAR1 in tumor cells may represent an effective strategy to impede tumor growth." (PMID 40244246, 2025). "CCK8 assay, soft agar clone formation assay, and transwell assays showed that HCAR1 overexpression enhanced the proliferation, tumor spheres, migratory, and invasive capabilities of MG‐63 and 143‐B cells, whereas HCAR1 knockdown substantially reduced these properties in both cell lines." (PMID 40956299, 2025). "HCAR1 may contribute to tumor development and progression through its regulation of lactate-mediated signaling pathways." (PMID 41050072, 2025). "Furthermore, a recent report indicates that lactate can drive tumor-induced cachexia through the HCAR1-Gi-Gβγ-RhoA/ROCK1-p38 signaling cascade." (PMID 40233099, 2025). "Interestingly, exclusion of HCAR1 from the nucleus has the same effect as its complete cellular depletion on tumor growth and metastasis in vivo." (PMID 39904567, 2025). "In addition to inhibiting lactic acid production and/or lactate import, antagonizing intracellular lactate signaling in malignant cells through HCAR1 also promotes anti-tumor effects." (PMID 37842241, 2023). "In addition, HCAR1 stimulation is seen to suppress MHC-II compromising tumour antigen presentation within T-cells preventing tumour recognition." (PMID 36615018, 2022). "However, elevated lactate levels activate the hydroxycarboxylic acid receptor 1 (HCAR1) on the tumour cell membranes, which promotes the production of mono-unsaturated fatty acids (MUFA) and inhibits ferroptosis." (PMID 36578477, 2022). "These actions may be related with direct and indirect HCAR1-mediated effects in tumor stromal cells." (PMID 33113952, 2020). "The ability of adipocytes to oxidize lactate is not surprising since adipocytes are highly equipped to respond to increased lactate stimulation from the tumor microenvironment through hydroxycarboxylic acid receptor 1 (GPR81) as well as through monocarboxylate transporter (MCT) facilitated influx." (PMID 33353120, 2020). "Lactate generated by glycolysis in the tumor cytoplasm undergoes regulated transport through specific receptors on the cell surface, primarily monocarboxylate transporters (MCTs), G-protein-coupled receptors (GPCRs), and hydroxycarboxylic acid receptor 1 (HCAR1)." (PMID 40244246, 2025). "Similarly, HCAR1 activation in lung cancer cells activated mechanisms that support the tumor immune evasion like an increased expression of the programmed death ligand 1 (PD-L1), a reduced production of interferon-γ or an increased apoptosis in cocultured Jurkat T-cell leukemia cells." (PMID 33113952, 2020). "Inhibiting HCAR1/MCT1 to block lactate uptake activates AMPK, downregulating SCD1 and promoting tumor ferroptosis." (PMID 40650086, 2025). "Contemporary research has unveiled that lactate is capable of engaging specific lactate receptors, G-protein-coupled receptor 81 (GPR81, also known as HCAR1) and GPR132 (G2A), thereby modulating downstream signaling cascades that influence tumor cell behavior." (PMID 40165895, 2025). "In the GSE19826 dataset, the tumor group’s expression levels of AKR1C2 and KRAS declined compared to the normal group; however, HCAR1 expression levels increased." (PMID 41050072, 2025). "In a murine CRC model, the antihypertensive agent reserpine is shown to block lactate-induced HCAR1 signaling, suppress the recruitment of CCR2 + PMN-MDSCs, restore CD8+ T cell-mediated antitumor immunity, and enhance tumor sensitivity to anti-PD-1 therapy." (PMID 41152975, 2025). "In CRC, HCAR1 signaling promotes the secretion of chemokines CCL2 and CCL7 by tumor cells, which in turn recruit CCR2+ PMN-MDSCs." (PMID 41152975, 2025). "The curcumin derivative NL01 was revealed to reduce HCAR1/MCT1 expression in OC cells and consequently induced ferroptosis in tumor cells, suggesting that NL01 is promising for application in OC therapy." (PMID 38440354, 2024).
tumor (continued). "In another study, TAZ was shown to transcriptionally upregulate PD-L1 via an upstream mechanism that involves tumor-cell-derived lactate and GPCR81 (also known as hydroxycarboxylic acid receptor 1, HCAR1) signaling." (PMID 36980211, 2023). "This study provides direct evidence on the anti‐ferroptotic roles of HCAR1 and MCT1 in tumor cells, highlighting their potential applications as molecular targets for ferroptosis‐based HCC therapy." (PMID 34632727, 2021). "Macrophages can sense lactate secreted from tumor cells via the G-protein-coupled receptors GPR132 (also known as G2A) and GPR81 (also known as hydroxycarboxylic acid receptor 1 (HCAR-1)) and respond with immunosuppressive activity." (PMID 31781212, 2019). "The present evidence indicates a correlation of HCAR1 and MCT genes expression with cancer cell survival in the tumour microenvironment." (PMID 26208712, 2015). "As seen with tumor volume, metastatic spread was observed only in HeLa cells expressing nuclear-intact HCAR1; no metastatic spread was detected in HCAR1 KD and N-HCAR1 KD cells." (PMID 39904567, 2025). "Lactate could stimulate HCAR1 (sometimes referred to as GPR81), a receptor that could potentially be utilized in specific tumor treatments." (PMID 39594672, 2024). "The lactate produced by tumor metabolism not only offers a favorable environment for tumor spread, but it can additionally inhibit ferroptosis in tumor cells by activating the Monocarboxylate Transporter 1 (MCT1) and Hydroxy-carboxylic Acid Receptor 1 (HCAR1)." (PMID 38994627, 2024). "In the intricate landscape of the tumor microenvironment, the signal transduction triggered by lactate stimulation mainly relays on the lactate receptor HCAR1 (GPR81), and proton-sensing G-protein coupled receptors (GPRs), including GPR4, TDAG8 (GPR65), OGR1 (GPR68), and G2A (GPR132)." (PMID 38576043, 2024). "Lactate activation of HCAR1 indeed suppressed STAT1/2 transcriptional activity and downregulated the expression of target genes, which might represent an intrinsic mechanism promoting tumor progression." (PMID 40956299, 2025).